RN7SKP90 (RN7SK pseudogene 90)
Gene: Miscellaneous RNA gene on chromosome 11 (16,842,253 to 16,842,587, forward strand). Ensembl gene ENSG00000199883.
Homologues: Orthologues: chimpanzee 7SK (99% identical). Paralogues in human: RN7SKP203 (76% identical), RN7SKP79 (74% identical), RN7SKP180 (73% identical), RN7SKP71 (73% identical), RN7SKP255 (72% identical), 7SK (72% identical), RN7SKP124 (72% identical), RN7SKP176 (72% identical), RN7SKP193 (71% identical), RN7SKP257 (71% identical), RN7SKP74 (71% identical), RN7SKP97 (71% identical), and 284 more.